MOG (myelin oligodendrocyte glycoprotein)
Diseases named in the same sentence as MOG in open-access papers (continued):
Sharing a sentence is not in itself a finding about the gene and the disease.
Autoimmunity (continued). "In this study, we investigated the uptake of malondialdehyde (MDA)-modified myelin oligodendrocyte glycoprotein (MOG) in the context of lipid peroxidation and its implications in CNS autoimmunity." (PMID 28828577, 2017). "Collectively, our results indicate that MOG-presenting viable and heat-inactivated C. utilis cells are able to generate an efficient myelin protection against CNS autoimmunity by the induction of oral tolerance." (PMID 27159446, 2016). "We describe the largest series to date of MOG-IgG-positive patients with brainstem involvement, thereby expanding the clinical spectrum of MOG-IgG autoimmunity." (PMID 27802825, 2016). "In part 3, we describe in detail the clinical course and presentation of a subgroup of patients with brainstem encephalitis and MOG-IgG-associated ON and/or LETM, a so far under-recognized manifestation of MOG-related autoimmunity." (PMID 27793206, 2016). "Coexisting autoimmunity in MOG-IgG-positive NMOSD seems to be rare compared with AQP4-IgG-positive NMOSD." (PMID 27793206, 2016). "By contrast, only around 9 % of our MOG-IgG-positive patients had a coexisting autoimmune disorder (2 × RA, 1 × Hashimoto thyroiditis, 1 × Grave’s disease)." (PMID 27793206, 2016). "To characterize the expression of IFNβ and a representative IFN-inducible gene (Isg56) in CNS autoimmunity over a long term period we immunized C57BL/6 N mice with MOG35–55 peptide (hereafter referred to as MOG) and characterized gene expression for 70 days." (PMID 25853624, 2015). "To characterize the anatomical localization of IFNβ producing cells within the CNS during autoimmunity we performed histological analyses of the spinal cord of IFNβmob/mob mice 17 days after MOG immunization." (PMID 25853624, 2015). "All these findings together suggested distinct roles for B cells in CNS autoimmunity and the importance of the differences in immune responses to MOG protein and peptide when choosing an EAE model for testing novel B cell-targeting agents for MS." (PMID 23300649, 2012). "Our results show that, unlike the previously reported HLA-DR-dependent susceptibility to MBP-, PLP-, or MOG-induced EAE, the pathogenic autoimmunity against PLP, as well as against MOBP, was dependent on HLA-DQB1*0602 rather than HLA-DRB1*1501." (PMID 22316121, 2012). "In a recent study to explore the role of the autoantigen in spontaneous autoimmunity, a transgenic mouse expressing a MOG-specific T cell receptor was investigated." (PMID 20927333, 2010). "HERVs present regions of similarity to myelin oligodendrocyte glycoprotein (MOG) and therefore could induce autoimmunity through the mechanism of molecular mimicry via cross‐humoral response." (PMID 40696868, 2025). "This revealed that cells arising from STOP:GP and MOG:GP mice occupied multiple clusters at comparable frequencies, indicating that brain-infiltrating B cells after long-term CNS autoimmunity are transcriptionally similar to steady-state B cells generated via infection." (PMID 36695896, 2023). "Thus, CNS-specific MOG CAR-Tregs exhibited enhanced protection against CNS-directed autoimmunity compared with DC1-specific XCR1 CAR-Tregs." (PMID 37965348, 2023). "In our study, it is tempting to speculate that MOGNR patients, which have higher Th17 in response to rh-MOG than MOGR at onset, can control autoimmunity since their Tregs are also increased upon rh-MOG stimulation." (PMID 34220827, 2021). "Ectopic MOG expression has also resulted in long-lasting protection from MOG-induced autoimmunity." (PMID 34149706, 2021). "Furthermore, we show that the B-cell populations had a significant role in building autoimmunity against MOG." (PMID 34130726, 2021). "In this study, Sun and colleagues describe a strategy to selectively remove MOG-specific antibodies that cause autoimmunity, without affecting the levels of protective antibodies of other specificities." (PMID 33212299, 2021).
Autoimmunity (continued). "Several studies have shown that the proportion of patients with autoimmunity against MOG among all patients with inflammatory demyelinating CNS disorders is age-dependent with the highest seropositivity rates and highest MOG-IgG titers found in very young children." (PMID 32883358, 2020). "For instance, our MOG encephalomyelitis patients who were suffered from seizures and/or encephalopathy also had a less female dominance, a relative lower coexisting autoimmunity rate, a better response to steroid and immunosuppression and a more benign prognosis compared with NMOSD and other IIDDs." (PMID 31080435, 2019). "Structural variables obtained using OCT help differential diagnosis in disorders that overlap clinically with MS, such as neuromyelitis optic spectrum disorders (NMOSD), myelin-oligodendrocyte-glycoprotein (MOG) seropositive autoimmunity or Susac syndrome (SuS)." (PMID 31816925, 2019). "During the pathological process of autoimmunity, the immune cells may erroneously attack MOG and NMDAR autoantigens, which are in the same location, and produce anti-NMDAR and anti-MOG antibodies in CSF and serum." (PMID 31866928, 2019). "Although the clinical spectrum of MOG Ab has been well explored, an in-depth characterization of the human MOG Ab response is lacking and is required to broaden our biological understanding of MOG Ab-associated autoimmunity." (PMID 31481127, 2019). "However more precise examination of the MOG expression and autoimmunity mechanism need to be performed." (PMID 28910378, 2017). "Accordingly, activation of TLR9 by endogenous ligands has been reported to be protective in autoimmunity, and TLR9-deficient mice exhibit exacerbated symptoms of myelin oligodendrocyte glycoprotein- (MOG-) induced EAE, as well as an enhanced susceptibility to experimental type 1 diabetes." (PMID 28356656, 2017). "We characterized B cell infiltration of the spinal cord in a B cell-dependent spontaneous model of central nervous system (CNS) autoimmunity that develops in a proportion of mice with mutant T and B cell receptors specific for myelin oligodendrocyte glycoprotein." (PMID 26441975, 2015). "As immune responses against myelin autoantigens, including myelin basic protein (MBP) and MOG, may be critical in MS pathogenesis, the formation of the myelin sheath around CNS axons may be an absolute requirement for CNS autoimmunity to occur." (PMID 23705890, 2013). "In addition, we induced EAE with myelin oligodendrocyte glycoprotein (MOG) to study the effect of chronic autoimmunity reaction in the context of the central nervous system in FINCA mice but did not detect any differences in clinical score development compared to WT litter mates (Appx." (PMID 40510178, 2025). "This suggests that disruption in MOG’s baseline structure may prevent autoimmunity." (PMID 39598329, 2024). "In addition, we could consider to use as induced tolerance-control the well-known autoimmunity-related protein such as myelin oligodendrocyte glycoprotein involved in autoimmunity in the experimental allergic encephalomyelitis." (PMID 39301030, 2024). "In this study, we analyzed public data to identify relationships between proteins or metabolites from microorganisms and the myelin proteins MBP and MOG, since such similarities may represent cases of molecular mimicry that contribute to autoimmunity and MS pathogenesis." (PMID 39775333, 2024). "A possible hypothesis for MOG and AQP4 antibody-associated autoimmunity triggered by a VZV infection is that the VZV infection causes a breakdown of the blood-brain barrier, as indicated by the common finding of an elevated CSF/serum albumin ratio in herpes zoster." (PMID 34737756, 2021). "This may mimic AQP4‐IgG and MOG‐IgG–related autoimmunity or seronegative NMOSD." (PMID 31187587, 2019).
Autoimmunity (continued). "There are some signals that B cells specific to the myelin surface antigen MOG might, through antigen-presenting cells, activate MOG-specific effector T cells either within the CNS or peripherally; and that there is age-dependent autoimmunity to MOG in MS." (PMID 29492266, 2018). "Thus, peripheral nerve insult by MOG-triggered autoimmunity may play an important role in EAE-induced neuropathic pain." (PMID 28181561, 2017). "It should be taken into account in both epidemiological and therapeutic studies in the future that optic nerve damage is the leading manifestation of MOG-IgG-positive autoimmunity and that MOG-IgG-positive patients may present for many years or decades with isolated ON." (PMID 27793206, 2016). "Together, this implies that i.c. infection with rLCMV-GP58 induced ASCs in the brain that persist weeks following viral clearance (STOP:GP group) and that are maintained during autoimmunity (aCD20-GFAP:GP and MOG:GP groups)." (PMID 36695896, 2023). "Investigation of AQP4 and astrocytes as targets of AQP4-IgG-mediated autoimmunity showed differences between AQP4-IgG and MOG-IgG EAE at acute disease stage." (PMID 37499337, 2023). "The main proteinaceous components of myelin, myelin basic protein (MBP), myelin oligodendrocyte glycoprotein (MOG), and proteolipid protein (PLP), are effective autoantigens and targets of autoimmunity in MS." (PMID 36614334, 2023). "The fact that vaccinations against different viruses have been reported in association with newly emerging MOG-EM, on the other hand, would argue in favour of (but not prove) the notion that vaccination is a non-specific trigger rather than the specific cause of MOG-directed autoimmunity." (PMID 35737110, 2022). "In the case of MS, peptides from the three major myelin proteins—myelin basic protein (MBP), myelin oligodendrocyte glycoprotein (MOG), and proteolipid protein (PLP)—have been identified to be related to autoimmunity." (PMID 33371329, 2020). "After immunization with myelin oligodendrocyte glycoprotein, WIM-6 mice on the C57BL/6 background exhibited intense IL6-luc luminescence in their brains and spinal cords due to autoimmunity against the myelin component (left)." (PMID 27211851, 2016). "We also assayed the ability of cultured LNCs from each of these mice to produce IFN-γ or IL-17, which are cytokines considered instrumental in autoimmunity and EAE, in response to restimulation with MOG." (PMID 24444311, 2014). "An extensive screening for CNS infections, autoimmune/paraneoplastic encephalitis, metabolic encephalopathy, and uremic hemolytic syndrome yielded negative results except for the detection of serum MOG-Abs (titer 1:320) using a live cell-based assay." (PMID 37360349, 2023). "Our direct comparison in animal models suggests a predilection for ventral neuroinflammatory lesions associated with AQP4-IgG and ventrolateral lesions in purely MOG-targeted autoimmunity regardless of MOG-IgG-augmentation." (PMID 37499337, 2023). "In particular, TNF alpha levels have been shown to be elevated in CSF in patients with AQP4 and MOG IgG autoimmunity, but not in patients with MS, and therefore the effect of TNF inhibition is likely different in these CNS inflammatory disorders." (PMID 36247761, 2022). "Previous studies found no autoimmunity in the CNS of Th mice even in case of high MOG-autoantibody titers, which was explained by an intact blood-brain barrier, hence we suggested that autoimmunity will also be absent in the visual system." (PMID 35140707, 2021). "This classical NMO definition may today segregate into AQP4‐IgG, MOG‐IgG and GFAP‐related autoimmunity or double seronegative NMOSD patients." (PMID 31187587, 2019). "The present study demonstrates that a protein from the human endogenous retrovirus HERV-W family (MSRV-Env) can be used instead of mycobacterial lysate to induce autoimmunity and EAE in mice injected with MOG, with typical anti-myelin response and CNS lesions normally seen in this model." (PMID 24324591, 2013).
Autoimmunity (continued). "Thus, mice immunized with IRBP or MOG (self) peptide, CFA and a PTX dose that facilitates the induction of autoimmunity had a strong immune response to these autoantigens yet exhibited a diminished or absent DTH reaction when challenged with the autopeptides." (PMID 20700542, 2010). "AQP4-IgG or MOG-IgG from the systemic circulation may enter the CNS through a disrupted blood–brain barrier, potentially initiating primary inflammatory events and damaging astrocytes, while GFAP autoimmunity may occur as a secondary phenomenon." (PMID 40777035, 2025). "The authors hypothesized a “spreading” autoimmunity as a possible mechanism, among others: in this scenario, the high inflammatory state in ADEM with a presumed presence of soluble MOG in CSF could possibly trigger an autoimmune mimicry with peripheral myelin proteins." (PMID 38035583, 2023). "Although coexisting of MOG-IgG and AQP4-IgG were found in a French cohort study, simultaneous involvement of MOG-IgG in the peripheral nervous system was thought to be unusual, and AQP4-IgG was only found in CSF, casting doubt on the existence of an overlap syndrome in GFAP autoimmunity." (PMID 37205100, 2023). "While overall there was a high degree of agreement between MRI findings and clinical presentation, in 5/15 (33.3 %) patients asymptomatic brainstem lesions were detected by MRI at least once, suggesting that subclinical brainstem encephalitis is not uncommon in MOG-IgG-related CNS autoimmunity." (PMID 27802825, 2016). "However, MOG 35-55 EAE in C57BL/6 mice is a mainly T cell-mediated model of autoimmunity where B cells do not play a vital role for mechanisms of tissue damage." (PMID 26438180, 2015). "This is also in line with rare cases of MOG-IgG coexisting with other autoantibodies (e.g., AQP4-IgG, NMDAR-IgG) where the clinical-MRI phenotype is typically predicted by the accompanying antibody, although overlapping features may occur (see also “Coexisting autoimmunity” above)." (PMID 35785363, 2022). "Cerebellar ataxia in NMDAR-E may not be explained by concomitant KLHL11, MOG, AQP-4, or GluK2 autoimmunity." (PMID 39735552, 2024). "Because aquaporin 4 antibodies and myelin oligodendrocyte glycoprotein antibodies were not tested in our patients, an NMO-like autoimmunity could not be completely excluded." (PMID 35370906, 2022). "Screening cell-based immunofluorescence assays revealed a higher frequency of MOG and MuSK autoantibody-positive samples compared with AChR or AQP4 (a total of 12/643 [1.9%], 8/643 [1.2%], 5/643 [0.8%], and 4/643 [0.6%] positive samples in the nonneurologic autoimmunity cohorts, respectively)." (PMID 30824481, 2019).
transverse myelitis (94 papers, 2014 to 2025). "Most patients with transverse myelitis associated with MOG-IgG have T2-hyperintense lesions on spinal MRI, with acute transverse myelitis often being longitudinally extensive." (PMID 40547008, 2025). "We report a rare case of a 40-year-old female with Behçet's disease who was treated with colchicine and developed two attacks of longitudinal extensive transverse myelitis, associated with positive serum anti-MOG antibodies." (PMID 41025024, 2025). "Contrast enhancement can be observed in some cases of myelin oligodendrocyte antibody-associated transverse myelitis (MOG-TM)." (PMID 39318613, 2024). "Autoantibodies targeting AQP4 and MOG are the most frequent causes of antibody-associated transverse myelitis." (PMID 36330423, 2022). "We present the case of a man with a first-time diagnosis of myelin oligodendrocyte glycoprotein- (MOG-) associated longitudinally extensive transverse myelitis (LETM), likely postinfectious in etiology, secondary to COVID-19 infection." (PMID 35399911, 2022). "Our case presented with VZV-associated longitudinally extensive transverse myelitis and had MOG-IgG at a titer of 1:1280." (PMID 34737756, 2021). "Four patients (7%) had primary progressive MS, 3 (5%) had radiologically isolated syndrome, 3 (5%) had aquaporin-4-IgG–positive NMOSD, and 1 (2%) had myelin oligodendrocyte glycoprotein-IgG–associated transverse myelitis." (PMID 32421186, 2020). "What clinical and radiological outcomes are associated with transverse myelitis in patients with myelin oligodendrocyte glycoprotein (MOG) antibody (Ab) disease or aquaporin-4 (AQP4)-Ab disease?" (PMID 31596489, 2019). "This is the first report of influenza A-associated longitudinally extensive transverse myelitis with a high titer anti-MOG antibodies." (PMID 25434485, 2014). "Myelin oligodendrocyte glycoprotein antibody-associated disease (MOGAD) is another condition that may cause transverse myelitis." (PMID 38807813, 2024). "Here, we describe a patient with MOG-IgG positive VZV-associated longitudinally extensive transverse myelitis (LETM), perform a study to determine the MOG-IgG frequencies in patients with VZV infection and neurological involvement and present the results of a literature review." (PMID 34737756, 2021). "This case supports the view that MOG antibodies are linked to longitudinally extensive transverse myelitis and that influenza infection might trigger the MOG antibodies." (PMID 25434485, 2014). "This patient's first clinical symptom was limb weakness, that different from previous reports of MOG antibody-related diseases, such as brainstem encephalitis, neuromyelitis optical, and transverse myelitis." (PMID 39220233, 2024). "The second patient, an 18-year-old black woman, presented with paraplegia and imaging revealed a longitudinally extensive transverse myelitis and had positive serum MOG antibodies." (PMID 37845760, 2023). "All 11 children (five in the MOG-seropositive group and six in the MOG-seronegative group) with transverse myelitis (TM) syndromes underwent spinal cord MRI." (PMID 37274199, 2023). "The diagnosis was shifted to longitudinally extensive transverse myelitis, and his CSF tested positive for MOG antibodies." (PMID 35399911, 2022). "It was reported that large and bilateral lesions and longitudinally extensive transverse myelitis (LETM) lesions were more common and more likely to resolve in MOG antibody-associated ADEM." (PMID 36352355, 2022). "Medullary involvement in subjects with anti-MOG antibodies appears to be characterized by longitudinal transverse myelitis." (PMID 33917395, 2021). "Transverse myelitis occurred at onset of disease for 32 patients (70%) with MOG-Ab disease and 57 patients (78%) with AQP4-Ab disease." (PMID 31596489, 2019).